CAPN3 (calpain 3)
Diseases named in the same sentence as CAPN3 in open-access papers (continued):
Sharing a sentence is not in itself a finding about the gene and the disease.
calpainopathy (continued). "Although the limited sample size prohibits us from making generalized statements, our findings leave open the possibility of mitochondrial enzyme dysfunction not being a universal feature of calpainopathy in humans, which appears to be the case in CAPN3 KO mice." (PMID 25079074, 2014).
muscular dystrophy (51 papers, 2008 to 2026). Muscular dystrophy (MD) refers to a group of more than 30 genetic diseases characterized by progressive weakness and degeneration of the skeletal muscles that control movement. "Limb-girdle muscular dystrophy R1 calpain 3-related (LGMDR1) is an autosomal recessive muscular dystrophy due to mutations in the CAPN3 gene." (PMID 37817200, 2023). "We report a family with calpain-related muscular dystrophy caused by two known variants in the calpain 3 gene (CAPN3, NM_000070.3; (I) c.700G>A, p.Gly234Arg and (II) c.1746-20C>G, p.)?" (PMID 37589857, 2023). "Several Capn3-deficient mouse models recapitulate to some extent the pathophysiological features of LGMDR1 muscular dystrophy." (PMID 35309930, 2022). "This is also supported by evidence in muscular dystrophy caused by a loss-of-function mutation in the calpain-3 gene that results in impaired ubiquitination and proteasomal degradation of damaged proteins, leading to muscle weakness and atrophy." (PMID 36393840, 2022). "The heterozygous missense variant found in CAPN3 was previously associated with muscular dystrophy, limb-girdle, autosomal recessive 1 (OMIM #253600)." (PMID 34125832, 2021). "Limb-girdle muscular dystrophy R1 calpain 3-related (LGMDR1) is an autosomal recessive muscular dystrophy produced by mutations in the CAPN3 gene that causes progressive degeneration of the proximal muscles of the pelvic and shoulder girdle." (PMID 34298987, 2021). "Limb-girdle muscular dystrophy R1 calpain 3-related (LGMDR1) is an autosomal recessive muscular dystrophy produced by mutations in the CAPN3 gene." (PMID 34298987, 2021). "Mutation in the CAPN3 gene leads to the most common form of autosomal recessive LGMD-2A type of Muscular Dystrophy." (PMID 34925456, 2021). "Limb-girdle muscular dystrophy type 2A (LGMD2A) is a form of muscular dystrophy caused bymutations in calpain 3 (CAPN3)." (PMID 27055500, 2016). "Other milder forms of muscular dystrophy are caused by mutations in genes coding the enzyme calpain 3 (LGMD2A), the sarcolemmal protein dysferlin (LGMD2B), and the sarcomeric protein telethonin (LGMD2G)." (PMID 25221510, 2014). "In humans, mutations of CAPN3 were shown to be responsible for muscular dystrophy by forward genetics, and an intron polymorphism of CAPN10 was reported to be associated with type 2 diabetes by statistical genetics." (PMID 20686710, 2010). "Capn3-deficient mice are fully fertile and viable and show a mild muscular dystrophy that affects a specific group of muscles." (PMID 20300593, 2009). "Most interestingly, our results reflect that SERCA1 and SERCA2 could be used as targets intherapeutic strategies for muscular dystrophies showing CAPN3 deficiency." (PMID 27055500, 2016). "The exact pathogenic mechanism that leadsmutations in CAPN3 to cause muscular dystrophy remains unclear butaccumulated evidence support a multifunctional role of CAPN3 in muscle homeostasis.Moreover, an efficient therapy is not currently available for LGMD2A patients." (PMID 27055500, 2016). "The pathological process due to calpain 3 deficiency is associated with alterations in membrane permeability suggesting the possible existence of a perturbation in homeostasis, especially in the intracellular Ca2+ concentration ([Ca2+]i) during muscular dystrophy." (PMID 20300593, 2009). "In contrast, CAPN3:CS KI mice showed greatly improved sarcomere organization, but still display mild muscular dystrophy with central nuclei and myofiber splitting." (PMID 40280419, 2025). "Dysregulated Ca handling linked to RyR dysfunction is reported in several muscular dystrophies, including Duchennes, dysferlin-related LGMD R2, β-sarcoglycan-related LGMD R4, and calpain 3-related LGMD R1." (PMID 41357548, 2025). "This study aims to clarify the phenotype of calpain 3-related muscular dystrophy in a family with three individual compound-heterozygous for two variants and two individuals heterozygous for one of them." (PMID 37589857, 2023).
muscular dystrophy (continued). "Both, recessive (LGMD R1) and dominant (LGMD D4) inheritance occur in calpain 3-related muscular dystrophy." (PMID 37589857, 2023). "Duchenne (DMD-OMIM310200) and Limb Girdle 2A/R1 (LGMD2A/R1-OMIM 253600) muscular dystrophies are caused by mutations in the DMD and CAPN3 genes, respectively." (PMID 35465312, 2022). "There is a muscle-specific calpain 3, known as p94, that is also involved in some muscular dystrophies." (PMID 35955530, 2022). "LGMD2A is an autosomal recessive human muscular dystrophy characterized by muscle wasting, cell death and decreased calpain-3 activity and expression." (PMID 35846001, 2022). "The significance of calpain-3’s interaction with titin was investigated in mice with muscular dystrophy with myositis (mdm) that showed an abrogation of calpain-3’s association with titin in addition to severe pathological phenotypes." (PMID 34299183, 2021). "The expression of the CAPN3 gene is involved in progressive muscular dystrophies during early human development." (PMID 32727368, 2020). "Insufficient Ankrd2 recruitment at the I-band has been observed in exercised mice affected by a progressive muscular dystrophy due to an inactivation of calpain 3 (CAPN3-KI mice)." (PMID 31428229, 2019). "Calpain 3 (CAPN3), also known as p94, is a skeletal muscle-specific member of the calpain family that is involved in muscular dystrophy; however, the roles of CAPN3 in muscular atrophy and regeneration are yet to be understood." (PMID 26569227, 2015). "Deficiency in a calpain can lead to disease: platelet dysfunction (calpain-1), muscular dystrophy (calpain-3), stress-induced gastric ulcer (calpains 8 and 9), and calpain-2 deficiency is embryonically lethal." (PMID 26527411, 2015). "Secondary reduction of calpain-3 protein can be observed in other types of muscular dystrophies." (PMID 38561828, 2024). "CAPN3 is an intracellular protease regulated by changes in calcium levels and plays a role in skeletal muscle degradation and sarcomeric remodeling, with defects resulting in muscular dystrophy." (PMID 26109061, 2015). "An automated process has been developed for the detection of deletions, duplications/insertions and point mutations in any gene or family of genes and has been applied to ten genes known to bear mutations that cause muscular dystrophy: DMD; CAV3; CAPN3; FKRP; TRIM32; LMNA; SGCA; SGCB; SGCG; SGCD." (PMID 19835634, 2009). "A recent study using a protease-inactive calpain 3 knock-in model, demonstrated that calpain 3 lacking protease functionality lead to muscular dystrophy, exacerbated by exercise." (PMID 22443334, 2012).
limb-girdle muscular dystrophy (44 papers, 2009 to 2025). Limb-girdle muscular dystrophy (LGMD) is a heterogeneous group of muscular dystrophies characterized by proximal weakness affecting the pelvic and shoulder girdles. "Autosomal dominant calpainopathy or limb girdle muscular dystrophy is a mild variant of the calpain 3 gene mutation mapped to chromosome 15 and presents in adulthood with involvement of pelvic girdle muscles, thigh, and axial muscles." (PMID 40520344, 2025). "Genetic analysis revealed a heterozygous mutation in CAPN3, suggestive of autosomal dominant calpainopathy or limb girdle muscular dystrophy." (PMID 40520344, 2025). "Recessively inherited limb-girdle muscular dystrophy type 1, caused by mutations in the calpain 3 gene, is the most common limb-girdle muscular dystrophy worldwide." (PMID 39703226, 2024). "Limb girdle muscular dystrophy R1 calpain 3-related (LGMDR1), due to mutations in the CAPN3 gene, is one of the most common autosomal recessive limb-girdle muscular dystrophies." (PMID 37817200, 2023). "With thousands of patients worldwide, CAPN3 c.550delA is the most frequent mutation causing severe, progressive, and untreatable limb girdle muscular dystrophy." (PMID 36865086, 2023). "Large numbers of Calpain 3 (CAPN3) mutations cause recessive forms of limb-girdle muscular dystrophy (LGMD2A/LGMDR1) with selective atrophy of the proximal limb muscles." (PMID 38020204, 2023). "Humans have three clp-4 orthologs, CAPN1 (calpain 1), CAPN2 (calpain 2) and CAPN3 (calpain 3), which have been implicated in limb-girdle muscular dystrophy." (PMID 37628820, 2023). "A muscle-specific calpain isoform (calpain-3) has also been reported where CAPN3 gene mutation has been implicated in limb-girdle muscular dystrophy in humans." (PMID 33276534, 2020). "CAPN3 deficiency is associated with limb-girdle muscular dystrophy, and its expression is also reduced in degenerating–regenerating mice model and during regeneration process." (PMID 32670085, 2020). "Loss-of-function mutations in the CAPN3 gene lead to the autosomal recessive form of limb-girdle muscular dystrophy (LGMD) type 2A (LGMD2A)." (PMID 33308300, 2020). "Among the genes affected is Calpain 3, which is mutated in limb girdle muscular dystrophy, a disease phenotypically similar to FSHD." (PMID 23300487, 2013). "Capn3 mutations have been found in the limb girdle muscular dystrophy (LGMD) type 2A." (PMID 32982660, 2020). "Limb-girdle muscular dystrophy (LGMD) is a progressive muscle weakness affecting the pelvic and shoulder girdles, primarily caused by mutations in proteins like myotilin, lamin, caveolin-3, calpain-3, dysferlin, γ-sarcoglycan, TCAP, TRIM32, FKRP, and titin." (PMID 39415830, 2024). "Calpain 3-related LGMD is the most common form of limb-girdle muscular dystrophy (LGMD) in most cases caused by biallelic variants in the calpain 3 gene (LGMD R1, CAPN3; equivalent to LGMD2A in the previous LGMD classification)." (PMID 37589857, 2023). "On identifying the relevant variants in the CAPN3, DYSF, and TCAP genes, the diagnosis was oriented toward limb-girdle muscular dystrophy (LGMD) in six patients from four families." (PMID 37377599, 2023). "Limb girdle muscular dystrophy (LGMD) 2A/R1, caused by mutations in the CAPN3 gene and CAPN3 loss of function, is known to play a role in disease pathogenicity." (PMID 34514031, 2021). "Mutations in CAPN3 are responsible for the subtype R1 of limb-girdle muscular dystrophy (LGMD)." (PMID 32971903, 2020). "Its interaction with both M-band Titin and Calpain 3 suggests its relevance to Limb-girdle Muscular Dystrophies." (PMID 27485725, 2016). "These myopathies are due to mutations in several genes, including dystrophin (Duchenne muscular dystrophy, DMD), calpain-3 (Limb girdle muscular dystrophies, LGMD2A), or titin [muscular dystrophy with myositis (MDM); tibial muscular dystrophy (TMD) and limb-girdle muscular dystrophy 2J (LGMD2J)]." (PMID 35846001, 2022).
limb-girdle muscular dystrophy (continued). "Currently, there is no cure or treatment for limb girdle muscular dystrophy R1 calpain 3-related." (PMID 34298987, 2021). "While the CAPN3 variant can explain adductor, posterior thigh weakness, and scapular winging, POMT1 variants are known to be associated with hypertrophic calves in limb-girdle muscular dystrophy (LGMDR11)." (PMID 33250842, 2020). "Limb-girdle muscular dystrophy recessive type 1 (LGMDR1, previously LGMD2A), caused by calpain 3 (CAPN3) gene variants typically resulting in loss of function of calpain 3 (CAPN3), is the most common recessive LGMD worldwide." (PMID 39703226, 2024). "Genetic screening for limb-girdle muscular dystrophy (LGMD) hotspot mutations (SGCG, FKRP, and CAPN3 genes) was negative." (PMID 40217903, 2025). "Further molecular genetic testing at age 9 for polyneuropathy, FSHD (facioscapulohumeral muscular dystrophy), and LGMD (limb-girdle muscular dystrophy) was negative (targeted testing of the CAPN3, FKRP and PMP22 genes was performed)." (PMID 36361862, 2022). "Limb girdle muscular dystrophy (LGMD) type 2A is caused by mutations in the CAPN3 gene and complete lack of functional calpain 3 leads to the most severe muscle wasting." (PMID 22443334, 2012). "For these individuals, mutation analysis was extended to include the seven most common limb-girdle muscular dystrophy (LGMD) genes (DYSF, CAPN3, SGCA, SGCB, SGCC, SGCD, and FKRP)." (PMID 31588416, 2017). "Loss of function mutations in CAPN3 have been linked with the autosomal recessive Limb-Girdle Muscular Dystrophy Recessive 1 (LGMDR1; OMIM: 253600 (formerly LGMD2A)) the most common form of LGMD worldwide, accounting for one third of all recessive cases with a prevalence of 1–9:100,000 (orpha.net)." (PMID 34740639, 2022).
dysferlinopathy (13 papers, 2008 to 2026). "While high CK levels in dysferlinopathies, dystroglycanopathies and sarcoglycanopathies are usually correlated with disease activity, calpain 3 deficient patients typically manifest mild to moderate CK level elevation." (PMID 24626787, 2014). "Moreover, both CAPN3 and dysferlin are closely associated with the Cav1.1–RyR complex, and in dysferlinopathy models, the Ca leak can be attenuated by dantrolene." (PMID 41357548, 2025). "CAPN3 gene mutations may contribute to dysferlinopathy symptoms, and dysferlin may act as a modifier gene in calpainopathies." (PMID 38540676, 2024). "In aged dysferlin null mice and individuals with dysferlinopathy, lack of dysferlin alters expression of many dysferlin-associated proteins including AHNAK, Annexin A2, Calpain-3, Caveolin-3 and MG53." (PMID 36653852, 2023). "Moreover, it has been observed that neither calpain-3 nor caveolin was consistently reduced in dysferlinopathies." (PMID 19015733, 2008).
Duchenne muscular dystrophy (11 papers, 2008 to 2024). Duchenne muscular dystrophy (DMD) is a neuromuscular disease characterized by rapidly progressive muscle weakness and wasting due to degeneration of skeletal, smooth and cardiac muscle. "The expression levels of the chaperones were measured in muscle tissue from controls and five hereditary myopathies with mutations in CAPN3 (LGMD2A), FLNC (MFM-filaminopathy), DMD (Duchenne muscular dystrophy), MYOT (MFM-myotilinopathy) or VCP (IBMPFD)." (PMID 28915917, 2017). "The fact that Capn3 E6- is already increased in pre-symptomatic FRG1 mice and that its expression is normal in the mouse model of Duchenne muscular dystrophy suggests that altered Capn3 splicing is a primary consequence of FRG1 overexpression and is not simply secondary to muscle wasting." (PMID 23300487, 2013).
melanoma (9 papers, 2010 to 2024). A malignant, usually aggressive tumor composed of atypical, neoplastic melanocytes. "The expression of two alternatively spliced short isoforms of CAPN3 has been observed before in melanoma, and the downregulation of these isoforms has been linked to melanoma aggressiveness and cisplatin resistance." (PMID 35883549, 2022). "We also included CAPN3, although AS was only detected by three tools, because of its association with cisplatin resistance and melanoma aggressiveness." (PMID 35883549, 2022). "In the present study, in order to investigate the pathophysiological role played by the longer Calpain-3 variant, hMp84, in melanoma cells, we over-expressed it in A375 and HT-144 cells." (PMID 25658320, 2015). "In melanoma cell lines and in melanoma biopsies, we have previously identified two novel splicing variants of CAPN3, namely hMp78 and hMp84 (GenBank accession number: EU91850 and EU91851, respectively)." (PMID 25658320, 2015). "In human melanoma cell lines and biopsies, we previously identified two novel splicing variants (hMp78 and hMp84) of Calpain-3 gene (CAPN3), which have a significant lower expression in vertical growth phase melanomas and, even lower, in metastases, compared to benign nevi." (PMID 25658320, 2015). "Therefore, it has been suggested that Capn3 may play a pro-apoptotic role in melanoma cells, and it could be a useful diagnostic marker for monitoring melanoma development and progression." (PMID 20421977, 2010). "Here, we show that melanoma cells with enforced expression of Calpain-3 experience a redox imbalance and, judging on their adverse cell fate (i.e. stimulation of cell death), we can say that they experience an oxidative stress." (PMID 25658320, 2015). "Since a more aggressive phenotype is expected to benefit from down-regulation of mechanisms impairing cell growth and survival, we envisage that Calpain-3 down-regulation can be regarded as a novel mechanism contributing to melanoma progression." (PMID 25658320, 2015). "Interestingly, shortened p62 forms of CAPN3 were recently found in melanoma cell extracts using anti-IS-1 and anti-IS-2 antibody." (PMID 34638951, 2021). "Nucleolar CAPN3 localization has also been reported in melanoma cells." (PMID 29507677, 2018). "In order to understand whether the observed cellular events required a potentially active Calpain-3, in selected experiments we overexpressed the mutant hMp84C42S (virtually devoid of its enzymatic activity) in both melanoma cell lines." (PMID 25658320, 2015). "A potential role of Calpain-3 in melanoma progression can be envisaged, consistently with our previous observations showing lower expression level (compared to benign lesions) of both Calpain-3 variants, hMp78 and hMp84, in vertical growth phase melanomas and, even lower, in metastases." (PMID 25658320, 2015). "Recent experimental studies have hypothesized a pro-apoptotic role of Capn3 in some melanoma cell lines." (PMID 20421977, 2010).
melanoma (continued). "The observation that melanoma cells do not tolerate long-lasting, high levels of such Calpain-3 variant was a starting and useful indication about the detrimental effect of this protease to melanoma cells, and prompted us to perform experiments in transiently over-expressing cells." (PMID 25658320, 2015). "Similarly, in melanoma, TRIM63 and CAPN3 are a direct target of MiTF, wherein TRIM63 mRNA expression was positively correlated with MiTF transcription factor and knockdown of MiTF decreased TRIM63 levels." (PMID 38393424, 2024). "We analyzed a few of the top DEGs (NRP2, CAPN3, DMBT1, BRAF, DDIT3, PPP1R3C, NF1) using The UCSC Xena platform that has large number of RNA-seq data of normal tissue from healthy individuals (GTEx) and primary tumor and metastatic tissue data from melanoma patients (TCGA)." (PMID 32983966, 2020). "High levels of Capn3 without any protease activity were detected in human melanoma cell lines." (PMID 20421977, 2010).
cardiomyopathy (5 papers, 2020 to 2024). A disease of the heart muscle or myocardium proper. "The proband A2 carrying a novel LMNA mutation presents both LGMD phenotype (which can be caused either by LMNA or CAPN3 mutation) and cardiomyopathy (not characteristic for LGMDR1)." (PMID 34720847, 2021).